BRAF (B-Raf proto-oncogene, serine/threonine kinase)
Diseases named in the same sentence as BRAF in open-access papers (continued):
Sharing a sentence is not in itself a finding about the gene and the disease.
pancreatic cancer (continued). "Active mutations in KRAS and BRAF, therefore, ultimately lead to the triggering of the MAPK signaling pathway, which is critical for the pancreatic cancer development." (PMID 36556296, 2022). "One patient with pancreatic cancer showed mutations in both the KRAS and BRAF genes, despite previous evidence that these mutations are mutually exclusive due to overlapping functionality." (PMID 35338679, 2022). "More than 90% of patients with pancreatic cancers have KRAS mutations, and BRAF deletion mutations are mutually exclusive with KRAS mutations." (PMID 35804932, 2022). "Aside from V600E, the rate of BRAF in-frame deletions with KRAS WT pancreatic cancer is shown to be 4.21%." (PMID 35804932, 2022). "Over 90% of pancreatic cancers are known to harbor activating KRAS mutations and the other 10% have oncogenic fusions, BRAF mutations, Receptor Tyrosine Kinase (RTK) mutations/amplifications, or AKT/mTOR activation." (PMID 34504655, 2021). "Of note, the mutual exclusivity of mutations was insignificant in pancreatic cancer, except for KRAS and BRAF genes." (PMID 33350171, 2021). "The discovery of recurrent fusions involving NRG1 in KRAS wild-type pancreatic tumors, as well as case reports of fusions involving BRAF, PRKACA, NTRK1/3, and RET, prompted us to systematically screen for fusion genes in this cancer entity." (PMID 33441414, 2021). "At present, one phase II clinical trial is exploring the effectiveness of encorafenib in combination with binimetinib for the treatment of BRAF-mutant pancreatic tumours (NCT04390243)." (PMID 33546207, 2021). "Mutations in other cancer-related genes, such as SMAD4, PI3KCA, PTEN, and BRAF, have been reported by previous studies in both IPMNs and pancreatic cancers with lower prevalence." (PMID 31338331, 2019). "Recently, PL + GEM was shown to induce apoptosis and inhibit BxPC-3 (KRAS wildtype, BRAF mutant) pancreatic tumor growth in a subcutaneous model." (PMID 29535819, 2018). "In a recent analysis of 2,400 pancreatic cancer patients of whom 82% were found to have mutated KRAS, mutations in BRAF, EGFR, HER2, FLT3, HRAS, PDGFRA, and PTEN were identified exclusively in KRAS wild-type patients, and even there, only rarely (8%)." (PMID 26161408, 2015). "Thus, KRAS and BRAF oncogenes may function in a mutually exclusive manner in the transformation and carcinogenesis of pancreatic cancers; indeed, some studies suggest that a mutation in one of these two genes invariably results in retention of wild-type copies of the other." (PMID 24624093, 2014). "Despite the presence of certain recurrent alterations, we were unable to hot spot mutations corresponding to studies in pancreas cancer, such as KRAS2 and BRAF." (PMID 25137133, 2014). "Still, the most pronounced responses were observed either in patients with already approved organ-specific drug indications (e.g., olaparib in BRCA1/2-driven pancreatic cancer), or in subjects with overtly actionable lesions (ALK fusions, BRAF V600E mutations, microsatellite instability, etc.)." (PMID 38612902, 2024). "Thus, the binding of ALA to MrgD in pancreatic cancer cell lines induces an antiproliferative effect by inhibiting the BRAF–MKK–ERK and PI3K–AKT pathways and activating FoxO1." (PMID 38338778, 2024). "BRAF has been found to be a driver gene/protein in some pancreatic cancers." (PMID 38607041, 2024). "Furthermore, the NCCN guidelines also recommended somatic testing of KRAS, BRAF, HER2, PALB2, MMR deficiency, and oncogenic gene fusions for pancreatic cancer patients with advanced or metastatic diseases." (PMID 36999792, 2023). "BRAF inhibitors showed activity in BRAF V600E mutated cholangiocarcinomas and pancreatic carcinomas in non-first line settings." (PMID 31221175, 2019).
pancreatic cancer (continued). "Intriguingly, although KRAS mutations are reported for 99% of PanIN-1s37, no more than 95% of pancreatic cancers have a KRAS or BRAF mutation, supporting the notion that a KRAS mutation is not strictly required for the development of pancreatic cancer." (PMID 28008139, 2017). "Interestingly, activation of ERKs in pancreatic cancer and cell reprogramming takes place at different levels of the pathway: upstream by RAS or BRAF mutations and at the level of MAP-kinases by Dusp6 downregulation, respectively." (PMID 27030341, 2016). "Hence, activating mutations of KRAS and BRAF ultimately result in activation of the MAPK signaling pathway, which is crucial for pancreatic cancer." (PMID 25699241, 2015). "Some pancreatic cancers have activating mutations in BRAF but not in KRAS." (PMID 36556296, 2022). "When applied to a large collection of published pancreatic cancer samples (n = 803), Arriba identified a variety of driver fusions, many of which affected druggable proteins, including ALK, BRAF, FGFR2, NRG1, NTRK1, NTRK3, RET, and ROS1." (PMID 33441414, 2021). "Another group used digital PCR to detect alterations in KRAS, BRAF, and PIK3CA in pancreatic cancer patients, demonstrating that detection of any of these genes was associated with lower progression-free survival." (PMID 29137355, 2017). "Moreover, some pancreatic cancers harbor activating mutations of BRAF rather than KRAS." (PMID 25699241, 2015). "Several theoretically “actionable” aberrations exist in pancreatic cancer including, but not limited to, KRAS, CDKN2A, ARID1A, BRCA, PALB2, PIK3CA, BRAF and so forth." (PMID 25714017, 2015). "EGFR pathway genes, including, EGFR, KRAS, BRAF, and PIK3CA genes, are well-investigated oncogenes in many tumors including lung, colorectal (CRC), and pancreatic cancers (PAC)." (PMID 19826477, 2009). "This pathway inhibition leads to the dephosphorylation and reduced activity of components like 3-phosphoinositide-dependent kinase 1, Akt1, and the mTOR receptor, as well as the BRAF/MKK/ERK1/2 signaling pathway, resulting in cell cycle arrest and apoptosis in pancreatic cancer cells." (PMID 40868211, 2025). "BRAF deletions are present in approximately 0.5%–1% of patients with pancreatic and thyroid cancers and account for about 5% in patients with KRAS wild-type pancreatic cancer." (PMID 39529955, 2024). "Cell migration and invasion have been proven to be important roles of CTEN, involving several proteins and signaling pathways, including KRAS/BRAF, Src/ROCK/SNAIL, ILK, and FAK in colorectal and pancreatic cancer, and Rho/ROCK/MLC in hepatocellular carcinoma, via DLC-1." (PMID 36851390, 2023). "The downregulation of SOX2 by 6-MITC and I7557 in PANC-1 pancreatic cancer cells harboring mutant K-ras may shed light on elucidating the interaction between SOX2, EGFR, and its downstream KRAS/BRAF and PI3K/AKT pathways." (PMID 24575144, 2014). "To determine whether RAF kinase rearrangements are recurrent events in pancreatic cancer, we performed break-apart FISH assays for both BRAF and RAF1, on TMAs containing 104 evaluable pancreatic cancer cases." (PMID 23637631, 2013).
colorectal tumors (122 papers, 2005 to 2025). "Approximately 80% of colorectal tumors harboring BRAF mutations (B-Raf-V600E) exhibit overexpression of the splice variant Rac1b." (PMID 40896432, 2025). "BRAF-mutated colorectal tumors are often microsatellite unstable and characterized by high DNA methylation levels." (PMID 40102611, 2025). "The metabolism/mitochondria activity score was confirmed as an independent positive parameter to predict the BRAF-V600E mutation status of colorectal tumors (multi-variable model: odds ratios: 6.53 and p-value = 3.32 × 10−5)." (PMID 41440935, 2025). "Colorectal tumors arising through the serrated neoplasia pathway often carry BRAF mutations and only rarely KRAS mutations." (PMID 39039804, 2024). "Specifically, BRAF mutations are found in a hotspot in exon 15 of colorectal tumors, which ultimately results in a single-amino-acid replacement of the V600E position." (PMID 39031216, 2024). "The application of radiomics in colorectal tumors, including the prediction of BRAF mutations, perineural invasion, lung metastasis, and response to chemoradiation, has been extensively studied." (PMID 39376912, 2024). "Research has linked specific clinicopathological features to serrated colorectal tumors that harbor BRAF mutations, MSI, and CIMP." (PMID 39031216, 2024). "For instance, colorectal tumors that are more common in Western populations include BRAF-mutated, CIMP, and MSI, in contrast to Eastern populations." (PMID 39031216, 2024). "We retrospectively reviewed the mutational profiles of 328 treatment-naïve colorectal tumors with BRAF mutations detected using capture-based hybrid next-generation sequencing targeting 400 + cancer-related genes." (PMID 36694231, 2023). "Taken together, our findings support the notion that BRAF-mutated colorectal tumors favor a strong immune activated state enriched with antigen-presenting cells and T lymphocytes, and therefore associates with MSI-H and CSM1 CRC tumors." (PMID 36975409, 2023). "Colorectal tumors in the proximal colon were reported to be more likely to have BRAF V600E mutations and the CIMP-high phenotype than tumors in the distal colon." (PMID 37107652, 2023). "High microsatellite instability (MSI-H) phenotype is also observed in malignant colorectal tumors closely related to BRAF proto-oncogene mutation via the methylation of cytosine at the CpG islands of BRAF gene promoter." (PMID 35743107, 2022). "Variant RAC1B is also overexpressed in a subtype of colorectal tumours, characterized by the presence of mutant BRAF and corresponding to up to 15% of all sporadic CRCs." (PMID 35326545, 2022). "Trametinib is effective in treating patients with colorectal tumors with BRAF V600E mutations and melanoma." (PMID 33858332, 2021). "According to the standard clinical protocol, BRAF V600E IHC or quantitative polymerase chain reaction was performed in MLH1-deficient colorectal tumors before or at the time of referral to exclude likely sporadic cancers." (PMID 34397043, 2021). "Several studies have found that smoking status has stronger associations with higher risks of MSI-high, CIMP-positive, or BRAF-mutated colorectal tumors but is less pronounced among MSI-low or microsatellite stable, CIMP-negative, or BRAF–wild-type CRC." (PMID 34377935, 2021). "Four somatic colorectal tumor markers were assessed individually and in combination, including BRAF mutation, KRAS mutation, CpG island methylator phenotype (CIMP), and microsatellite instability (MSI) status." (PMID 34377935, 2021). "Even though BRAF and KRAS work close in the EGFR pathway, their mutations result in different gene expression patterns, with an even greater heterogeneity found among BRAF mutated mCRC, as shown in a study of 218 BRAF-V600E mutated colorectal tumors." (PMID 32545884, 2020). "One example is its ability to inhibit the alternative splicing event generating RAC1B, which is overexpressed in a specific subset of BRAF-mutated colorectal tumors and sustains cell survival." (PMID 33315986, 2020).
colorectal tumors (continued). "The BRAF V600E mutation was reportedly found in 8–10% of colorectal tumors and was associated with a more aggressive tumor phenotype, lymph node metastasis, and high microsatellite instability (MSI)." (PMID 33076847, 2020). "BRAF Val600Glu mutation occurs in ~ 10% of the colorectal tumors, causes oncogenic BRAF activity, and promotes cellular transformation." (PMID 31352904, 2019). "This overexpression of RAC1B in colorectal tumors induces cell cycle progression and cancer cell survival, and has been associated with the BRAF-V600E mutation." (PMID 30621237, 2019). "All 4 treatments produced meaningful responses, with particularly notable objective response rates in patients with human EGFR-2–amplified/overexpressing colorectal tumors (38%) and BRAF V600-mutated NSCLC (43%)." (PMID 29765547, 2018). "From these results, it can be inferred that colorectal tumours with the BRAF mutation can shrink visibly but the PFS was shorter during systemic chemotherapy." (PMID 29662660, 2018). "Previous studies observed CIMP-high and BRAF mutations in an early-stage colorectal neoplasm, and acquisition of BRAF mutation was considered to be mediated by DNA hypermethylation of several genes, including IGFBP7 and BMP3." (PMID 28623901, 2017). "The stability and reproducibility over time of the BRAF mutation-like 58-gene signature in FFPE samples was measured over 40 independent measurements using 2 FFPE colorectal tumor control samples; one known BRAF mutated tumor and one BRAF wild-type tumor." (PMID 29479053, 2017). "BRAF mutations of these 302 colorectal tumors were measured: as expected, within the pre-screened 96 tumors, a high percentage 35.4% (n = 34) harbored p.V600E mutations, and within the randomly selected 206 tumours, 11.2% (n = 23) harboured p.V600E mutations." (PMID 29479053, 2017). "On the other hand, concomitant KRAS and BRAF-mutated colorectal tumors are relatively rare, so that the routine analysis of BRAF mutations in tumors with the KRAS mutations is not recommended." (PMID 28580315, 2017). "Weisenberger and colleagues identified a robust five-gene panel that recognized a distinct, heavily methylated subset of colorectal tumors that were also characterized by the BRAF mutation and MSI." (PMID 29075358, 2017). "Performance of the BRAF mutation-like 58-gene signature was estimated by a leave-one-out cross-validation (LOOCV) on the set of 302 FFPE colorectal tumor samples." (PMID 29479053, 2017). "These analyses demonstrated that a MMR gene variant present in an MSI-H colorectal tumour has ~7–9-fold chance of being disease-causing, and if also wild-type BRAF the likelihood of being disease-causing increases to 12 to13-fold." (PMID 25831438, 2015). "Presence of the oncogenic BRAF V600E mutation in colorectal tumours can also be used to indicate spontaneous cases, but it is not a useful marker for triaging endometrial tumours." (PMID 25831438, 2015). "In this study, we aim to elucidate the frequency of KRAS mutation and BRAF mutation in polypoid, flat and depressed colorectal neoplasms and compare these morphological counterparts each other." (PMID 25551625, 2014). "The colorectal tumours arising from serrated polyps have BRAF mutations, CpG island methylation, and often high levels of microsatellite instability (MSI-H)." (PMID 24812557, 2014). "BRAF mutations have long been connected with microsatellite instability (MSI) in sporadic colorectal tumours, because mismatch repair-deficient tumours have a very high incidence of BRAF mutations." (PMID 25361007, 2014). "Caco-2 cells contain the wild-type of two other oncogenes, K-ras and BRAF, mutations of which are present in 45% and 15% of colorectal tumours respectively." (PMID 24180698, 2013). "We studied genome-wide DNA methylation differences between colorectal tumors carrying a BRAF mutation and BRAF wildtype tumors." (PMID 23324568, 2013).
colorectal tumors (continued). "This study has analyzed in detail the role of BRAF/ KRAS/ PIK3CA mutation status of particular colorectal tumours on predicting efficient therapeutic treatments with the BRAF and the PI3K inhibitors as well as their rational combination with TRAIL." (PMID 21738740, 2011). "We previously identified the CIMP status and BRAF mutation status of 235 primary colorectal tumor samples." (PMID 20027224, 2009). "In conclusion, we demonstrated that RASSF2 methylation is of importance as well as K-ras/BRAF mutations during the progression of colorectal tumours." (PMID 17923875, 2007). "Raf is a major proliferative and antiapoptotic effector, and it was recently shown that BRAF, one of the Raf kinases, is frequently activated by mutation in human tumours, particularly melanomas (∼70%) and colorectal tumours (∼15%)." (PMID 17923875, 2007). "The aim of the present study was to evaluate the clinical, pathological and molecular phenotype of colorectal tumors with BRAF mutations." (PMID 16403224, 2006). "It is also known that colorectal tumours with BRAF gene mutations, specifically V600E mutation, have an unfavourable prognosis but may partially respond to treatment with BRAF inhibitors and anti-EGFR antibodies." (PMID 39996841, 2025). "KRAS and BRAF mutations are generally mutually exclusive in colorectal tumors." (PMID 38786305, 2024). "Furthermore, mutations in KRAS, NRAS, and BRAF are mutually exclusive in colorectal tumours, and it has been reported that patients with BRAF and NRAS modifications have considerably shorter survival rates." (PMID 36612217, 2022). "One example is the alternative splicing variant Rat Sarcoma Viral Oncogene Homolog (Ras)-Related C3 Botulinum Toxin Substrate 1 (RAC1)B, which we previously identified in a subset of V-Raf Murine Sarcoma Viral Oncogene Homolog B (BRAF)-mutated colorectal tumours." (PMID 35326545, 2022). "Furthermore, the study found that TRAP1/HSP90 inhibitors led to a decrease in BRAF, with this effect appearing more pronounced in colorectal tumor cell lines with the BRAFV600E mutation, suggesting that TRAP1 plays a key role in maintaining BRAF expression." (PMID 34831420, 2021). "RAC1B results from the in-frame inclusion of an alternative exon 3b, which produces a highly activated variant that is overexpressed in a specific subset of colorectal tumors, characterized by a serrated polyp morphology and the presence of activating mutations in BRAF." (PMID 33315986, 2020). "Colorectal tumours identified by this 58-gene signature are called the BRAF mutation-like subtype." (PMID 29479053, 2017). "Arbitrary selected 75 colorectal tumors were analyzed for BRAF, KRAS, and NRAS gene mutations." (PMID 28460459, 2017). "In order to gain a better understanding of molecular characteristics of these patients and design a personalized treatment for them, we have previously developed a 58-gene signature that characterizes the gene expression pattern of BRAF-mutated colorectal tumors." (PMID 29479053, 2017). "Moreover, the co-occurrence of KRAS and BRAF mutations in the same colorectal tumor has been reported in few studies." (PMID 28580315, 2017). "CIMP high colorectal tumors are more prevalent in women and are associated with BRAF mutations." (PMID 26106599, 2015). "Activation of RAS signalling induced by K-ras/BRAF mutations is a hallmark of colorectal tumours." (PMID 17923875, 2007). "In summary, our study presents a promising treatment strategy for patients with wild-type KRAS/NRAS/BRAF colorectal tumors." (PMID 39905540, 2025).